LGALS3 (galectin 3)
Diseases named in the same sentence as LGALS3 in open-access papers (continued):
Sharing a sentence is not in itself a finding about the gene and the disease.
heart failure (continued). "Specifically, future studies should clarify the relationship between serum galectin-3 and cardiovascular mortality and evaluate additional endpoints, such as the incidence of heart failure, atrial fibrillation and sudden cardiac death." (PMID 38519721, 2024). "Targeting galectin-3 signaling pathways holds significant promise as a therapeutic strategy for managing diastolic dysfunction and enhancing clinical outcomes in heart failure." (PMID 39063659, 2024). "Promising novel biomarkers that showed good performance in detecting diastolic dysfunction or heart failure in diabetic patients include galectin-3, ST2, FGF-21, IGFBP-7, GDF-15, and TGF-β." (PMID 39335666, 2024). "Galectin-3 (Gal-3) is the most studied galectin in cancer research, is involved in fibrosis and inflammation and plays a role in heart failure, renal disease, obesity and cancer." (PMID 39769262, 2024). "Galectin-3 is a relatively new biomarker that is well studied as a promoter of cardiac inflammation and fibrosis leading to heart failure." (PMID 38535084, 2024). "Serum levels of galectin-3 are rarely variable; once elevated, they often remain elevated and are unaffected by standard heart failure treatment." (PMID 39346100, 2024). "Galectin-3 (Gal-3) has emerged as an important biomarker due to its key role in cardiac remodeling and heart failure alongside NT-proBNP and BNP, which was demonstrated in a recent meta-analysis ​, and more recently in PE." (PMID 39587642, 2024). "They showed that galectin-3 is the dominantly overexpressed gene in those animals that went on to develop overt heart failure." (PMID 37513890, 2023). "In the same study, using homozygous transgenic TGRmRen2-27 (Ren-2) rats, a heart failure-prone hypertensive model, these authors demonstrated that galectin-3 was upregulated in the heart following the development of heart failure." (PMID 37513890, 2023). "Neutralization of Galectin-3 mitigates fibrosis, left ventricular dysfunction, and the development of heart failure." (PMID 37513890, 2023). "Our study and the studies cited above ascertained an association between a history of coronary heart disease and elevated galectin-3 in patients with heart failure." (PMID 36673621, 2023). "Circulating galectin-3 levels were higher in type 2 diabetes, heart failure, macroalbuminuria, cardiovascular diseases and certain types of cancer such as colorectal and gastric cancer." (PMID 37189804, 2023). "It was also reported that high urinary galectin-3 levels in patients with heart failure were a prognostic factor for renal dysfunction and death." (PMID 37189804, 2023). "The inhibition of galectin-3 by N-Lac attenuates cardiac fibrosis and improves left ventricular function and subsequent heart failure." (PMID 37513890, 2023). "Several factors, such as time to the detection of heart failure, NT-proBNP level, left ventricular systolic function (EF), and pre-treatment plasma galectin-3 concentration, showed a linear correlation (p < 0.05)." (PMID 36673621, 2023). "Our studies focused on periostin, a unique and major contributor of ECM remodelling in the heart; and galectin-3, an established biomarker of heart failure that binds ECM components and transduces or modulates fibrogenic signalling cascades." (PMID 36968272, 2023). "Novel biomarkers such as PENK, ST-2, GDF-15, Pentraxin-3, Galectin-3, and Osteopontin have recently emerged as potential prognostic indicators in heart failure patients." (PMID 36902318, 2023). "Galectin-3 participates in inflammation, fibrosis, and neoplastic transformation, establishing it as a marker of heart failure." (PMID 37176751, 2023). "In patients with heart failure, mean plasma galectin-3 levels were 1.7-fold higher compared to healthy controls, while urinary galectin-3 levels in these two groups were comparable." (PMID 37189804, 2023).
heart failure (continued). "Elevated Galectin-3 level is a predictor of the development of acute ischemic events and heart failure in diabetic patients as well as diabetic cardiomyopathy with depressed cardiac function." (PMID 37240345, 2023). "There are scarce data regarding ongoing clinical trials testing galectin-3 inhibitors to treat heart failure." (PMID 37685918, 2023). "Both galectin-3 and sST2 concentrations showed significant correlation with the echocardiographic markers of LV or LA size and function in heart failure patients." (PMID 35042522, 2022). "Along with brain natriuretic peptide (BNP), galectin-3 has been shown as a good prognostic factor in heart failure with both preserved and reduced left ventricular ejection fraction." (PMID 35626917, 2022). "In heart failure, systemic IL-33 R and galectin-3 were described as markers of left ventricular hypertrophy with reduced ejection fraction, as well as independent predictors for ischemia." (PMID 36362577, 2022). "Another study demonstrated that galectin-3 is an independent predictor of mortality and development of heart failure in patients with previous AMI47." (PMID 36307429, 2022). "A pooled analysis of data from three cohorts (COACH, PRIDE, and UDM H-23258) showed that plasma galectin-3 concentration > 17.8 ng/ml was predictive of rehospitalizations in heart failure patients." (PMID 36272642, 2022). "Galectin-3 is a member of the beta galactoside binding lectin family involved in cardiac fibrosis, heart failure (HF) and atherosclerosis." (PMID 36551214, 2022). "They provided evidence for the utility of combining analysis of BNP, hsTroponin-I, and galectin-3 in the prediction of future heart failure with preserved ejection fraction." (PMID 35410028, 2022). "CRP and IL-6 are common inflammatory mediators that are mainly produced by activated macrophages, whereas galectin-3 is a newly discovered inflammatory marker of heart failure and is produced by macrophages." (PMID 35356068, 2022). "In another study, however, MCP ameliorated cardiac dysfunction, reduced collagen deposition, and decreased myocardial injury, and galectin-3 expression in a rat model of heart failure." (PMID 36272642, 2022). "The plasma galectin-3 level is considered to be a good biomarker for the prediction and prognosis of left ventricular systolic dysfunction and heart failure in diabetic patients." (PMID 35069790, 2022). "Galectin-3 has been approved as a supplementary indicator for prognosis of patients with heart failure in 201045 despite certain contradictions in the data of clinical investigations." (PMID 36307429, 2022). "A potential and promising direction for research is galectin-3 concentrations in children with congenital heart diseases, heart failure symptoms, arrhythmias or myocarditis." (PMID 35410028, 2022). "The role of Galectin-3 as a prognostic marker of heart failure is described, and the tentative use of Galectin-3 inhibition is a potential therapeutic approach to prevent cardiac inflammation and fibrosis." (PMID 35083706, 2022). "The present promising results have to be confirmed in future studies which need to further assess the role of galectin-3 in heart failure especially regarding individuals with impaired glucose metabolism." (PMID 34561496, 2021). "Chen A, Hou W, Zhang Y, Chen Y, He B. Prognostic value of serum galectin-3 in patients with heart failure: a meta-analysis." (PMID 33656072, 2021). "Other studies made similar observations, and galectin-3 has been approved for prognostic use in heart failure in the United States." (PMID 35141299, 2021). "The inhibiting effect of MCP on LGALS3 gene expression was tested in cardiac fibroblasts in a rat experimental model of heart failure." (PMID 35053194, 2021). "Galectin-3 >15.974 ng/mL identified heart failure with preserved ejection fraction with 76.0% sensitivity and 71.9% specificity." (PMID 35141299, 2021).
heart failure (continued). "To date, only one study is available to compare the dynamic changes of galectin-3 and sST2 in adults and children with heart failure requiring VAD." (PMID 33513858, 2021). "Galectin-3 is a prognostic biomarker in heart failure and an essential mediator for cardiac fibrosis." (PMID 34588985, 2021). "Galectin-3 is a contributing factor to cardiac fibrosis, and a biomarker for LV remodeling and heart failure progression." (PMID 34212014, 2021). "For assessment of validity and diagnostic value of galectin-3 in prediabetes and T2DM in comparison to an established biomarker of heart failure, the results of galectin-3 were compared to NT-proBNP." (PMID 34561496, 2021). "The effect of galectin-3 is closely related to the heart failure markers useful in clinical practice, namely natriuretic peptides." (PMID 35053194, 2021). "Higher values (>15.3 ng/mL) of galectin-3 have been reported to show a correlation with the severity of heart failure." (PMID 33513858, 2021). "In this review, we provide an overview of the recent clinical interpretation of galectin-3 and sST2 and emphasize their similarities and differences for the prognostic prediction of heart failure requiring ECLS." (PMID 33513858, 2021). "It was shown that in patients with heart failure a reduction of miR-1 and miR-21 expression occurred, and these results were significantly correlated with the concentration of serum galectin-3, the important factor playing the key role in the fibrotic process." (PMID 35053194, 2021). "al. as the point in time Galectin-3 baseline measurement was on average 12 years before heart failure diagnosis." (PMID 33563287, 2021). "The participation of the mentioned miR-1, miR-21 and serum galectin-3 concentration was also studied in patients with symptomatic heart failure and left ventricular hypertrophy and history-confirmed arterial hypertension." (PMID 35053194, 2021). "In individuals with T2DM, increasing galectin-3 levels were associated with reduced systolic and diastolic function after adjustment for age, sex, traditional CVRF, comorbidities and intake of heart failure medication." (PMID 34561496, 2021). "The diagnostic usefulness of the miR-1 and miR-21, known in the pathogenesis of heart failure, and of galectin-3 protein was analysed in a group of patients with acute heart failure and coexistent asymptomatic type 2 diabetes mellitus." (PMID 35053194, 2021). "In population studies, patients with higher basal galectin-3 level were more likely to lead to new-onset heart failure." (PMID 35141299, 2021). "Serum galectin-3 concentration was significantly higher in the heart failure group compared with the control group." (PMID 35141299, 2021). "In heart failure galectin-3 is released into extracellular space, promoting fibrotic process through activation of fibroblasts." (PMID 35053194, 2021). "One of the biomarkers introduced in the clinic relatively recently and used in the assessment of patients with heart failure and AF is galectin-3 (gal-3)." (PMID 34439775, 2021). "With respect to heart failure with preserved ejection fraction, galectin-3 was shown to be of particular importance." (PMID 34561496, 2021). "One study found that for each 1-ng/mL increase in galectin-3 concentration, the rate of heart failure readmission increased by 18%." (PMID 35141299, 2021). "Neither galectin-3 and/or sST2 has been examined as guides for adjusting medical management for heart failure in pediatric patients, and thus the role of galectin-3 and /or sST2 as a guide to therapeutic decision-making remains to be established." (PMID 33513858, 2021). "Although the mechanism of action of galectin-3 in the progression of heart failure has been clarified, determining how to use this biomarker still requires investigation." (PMID 35141299, 2021).
heart failure (continued). "The studies regarding application of galectin-3 in pediatric patients with heart failure requiring ECLS are quite scarce compared to adult patient populations and all the studies only evaluate VAD patients." (PMID 33513858, 2021). "There was a correlation between galectin-3 and heart failure with preserved ejection fraction, and galectin-3 was an independent predictor of heart failure with preserved ejection fraction." (PMID 35141299, 2021). "Over the last decade there has been a marked increase in the understanding the role of galectin-3 in myocardial fibrosis and inflammation and as a therapeutic target for the treatment of heart failure and myocardial infarction." (PMID 35053194, 2021). "The purpose of this study was to investigate the utility of BNP, hsTroponin-I, interleukin-6, sST2, and galectin-3 in predicting the future development of new onset heart failure with preserved ejection fraction (HFpEF) in asymptomatic patients at-risk for HF." (PMID 33563287, 2021). "The expression of osteopontin increases with the severity of heart failure and seems to be a major regulator of myocardial remodeling where it potentiates galectin-3 up-regulation and secretion." (PMID 33344515, 2020). "This study aimed to assess the value of galectin-3 assay in early diagnosis of children with heart failure secondary to congenital heart disease (CHD) and correlate it with the patients’ outcome." (PMID 33248453, 2020). "This study aimed to assess the value of galectin-3 assay in early diagnosis of children with heart failure secondary to CHD and correlate it with the patient’s outcome (mortality)." (PMID 33248453, 2020). "The continuously increasing level of heart failure biomarkers (NT-proBNP and galectin-3) in the placebo group can be a consequence of the progression of the disease." (PMID 33187089, 2020). "A significant increase of galectin-3 secretion (a prognostic biomarker in patients with heart failure) was observed immediately after a 10 km run, a half-marathon, and a marathon in a dose–response manner." (PMID 33066215, 2020). "In the clinical setting, galectin-3 has been established as a biomarker of adverse left ventricular remodeling and heart failure morbidity and mortality." (PMID 31885743, 2019). "Galectin-3 (Gal-3) is a fibrosis biomarker that is involved in the initiation and progression of many fibrosis related diseases, such as heart failure (HF), live cirrhosis, and lung fibrosis." (PMID 31772609, 2019). "Galectin-3 inhibitor was investigated to be applied to the fields of heart failure, cancer, and nonalcoholic steatohepatitis." (PMID 31080833, 2019). "The goal of this study is to determine the cardiac localization and the time-course of galectin-3 expression in heart failure after viral inoculation with EMCV." (PMID 30673749, 2019). "Elevated serum levels of galectin-3 are strongly associated with increased morbidity and mortality from CVD and heart failure." (PMID 30587230, 2018). "The potential role of galectin-3 as a circulating biomarker for cardiovascular diseases has been mainly tested in patients with heart failure." (PMID 29327139, 2018). "Galectin-3, a biomarker of fibrosis, is elevated both in patients with heart failure and persistent atrial fibrillation." (PMID 30067817, 2018). "Diagnostic and treatment algorithms incorporated predictive values of Galectin-3 (Gal-3) and interleukin-33 (IL-33) in treatment of coronary diseases and heart failure and evaluating prediabetic state." (PMID 29988422, 2018). "Galectin-3 is demonstrated to be a robust independent marker of cardiovascular mid-term (18-month) outcomes in heart failure (HF) patients." (PMID 30262779, 2018). "In clinical settings, plasma galectin-3 levels are increased and considered to be a strong prognostic biomarker in patients with heart failure." (PMID 29414883, 2018). "Suppression of tumorigenicity 2 (ST2) and galectin-3 (GAL-3) are emerging biomarkers in the field of heart failure." (PMID 31435501, 2017).
heart failure (continued). "Numerous studies of heart failure have shown the prognostic significance of the increased galectin-3 plasma concentration, in the prediction of an unfavorable outcome." (PMID 29118378, 2017). "It has been shown the even higher predictive significance of galectin-3 plasma levels in the patients with heart failure and preserved LVEF17,32." (PMID 29118378, 2017). "An independent relation between increased galectin - 3 levels and mortality and/or heart failure was found." (PMID 29118378, 2017). "Currently, attempts are being made to target or inhibit galectin-3 using natural or pharmaceutical inhibitors with the aim to ameliorate heart failure." (PMID 31435501, 2017). "Suppression of tumorigenicity 2 (ST2) and galectin-3 are new emerging biomarkers in the field of heart failure in both the general and dialysis populations." (PMID 31435501, 2017). "Galectin-3 (Gal-3) is an independent predictor of poor outcomes and mortality in patients with heart failure (HF)." (PMID 29180917, 2017). "Increasing evidence indicates a role for galectin-3 in cardiovascular fibrosis and cardiac dysfunction and levels of this biomarker are now being used clinically as a predictor of heart failure." (PMID 28478264, 2017). "Of the novel biomarkers below, serum galectin-3 has been adopted by some academic institutions during routine clinical evaluation of heart failure." (PMID 28493232, 2017). "Galectin-3 is thought to enhance fibrosis, a central process in both maladaptive cardiac remodeling and heart failure." (PMID 28066244, 2016). "In rodent models, myocardial galectin-3 expression can predict future heart failure, while the administration of exogenous galectin-3 can promote fibrosis and heart failure." (PMID 27089335, 2016). "It was demonstrated in animal models that galectin-3 contributes to the development and progression of heart failure through cardiac fibrosis and adverse structural remodeling." (PMID 28044067, 2016). "In a series of clinical and experimental evidences, galectin-3 has been involved in fibrosis, heart failure, obesity, impaired glucose metabolism, and cancer." (PMID 27089335, 2016). "Galectin-3 inhibition also attenuated cardiovascular fibrosis and left ventricular dysfunction in a mouse model of heart failure." (PMID 27118293, 2016). "Activation of PKC pathway promotes galectin-3 expression and cardiac fibrosis in HL-1 cardiomyocytes and in heart failure hearts." (PMID 28066244, 2016). "Galectin-3 is a marker of myocardial inflammation and fibrosis shown to correlate with morbidity and mortality in heart failure (HF)." (PMID 27301475, 2016). "The glycoprotein Galectin-3 was also up regulated, this protein induces fibrosis in animal models and has been proposed as a biomarker for prognosis and management in heart failure." (PMID 26876649, 2016). "Galectin-3 knockout mice showed decreased fibrosis and preserved cardiac function in response to heart failure induction compared to controls." (PMID 28066244, 2016). "Galectin-3 as a part of this lectin family plays a very important role in development of heart failure." (PMID 25960597, 2015). "According to recent papers, galectin-3 plasma level correlates with heart failure outcome, primarily with rehospitalisation and death from heart failure." (PMID 25960597, 2015). "Galectin-3 has been studied for putative roles in heart failure, fibrosis, cancer, angiogenesis, and atherosclerosis." (PMID 26047815, 2015). "Galectin-3 (Gal-3) is considered as a myocardial fibrosis biomarker with prognostic value in heart failure (HF)." (PMID 25786035, 2015). "Galectin-3 (Gal-3) is an emerging biomarker in heart failure that is involved in fibrosis and inflammation." (PMID 25875595, 2015). "When taking into consideration importance of galectin-3 in heart failure pathophysiology, certainly we have to exclude the impact of these conditions on the final conclusions." (PMID 25960597, 2015).